INS (insulin)
Diseases named in the same sentence as INS in open-access papers (continued):
Sharing a sentence is not in itself a finding about the gene and the disease.
diabetes (continued). "A total of 304 patients (females 52.6%, mean age 57.4 ± 10.9 years, BMI 27.3 ± 4.8 kg/m2, median duration of diabetes 14 years, baseline A1C 7.2 ± 1.3%, and insulin treatment 21%) participated in the study." (PMID 30671482, 2018). "In this sense, a common method of suicide attempt in T2DM patients is use of high doses of insulin and other medications for treating diabetes." (PMID 29880751, 2018). "Diabetes was defined as adult onset, controlled with diet or insulin, or juvenile onset as described by SVS reporting standards." (PMID 30643506, 2018). "A form of diabetes known as neonatal diabetes, where the body stops making insulin, usually appears during the first six months of life." (PMID 30412052, 2018). "In Canada, mean A1C levels are > 8.5% and mean diabetes duration is ≥ 9 years before initiation of basal insulin in T2D patients." (PMID 29476414, 2018). "Diabetes mellitus (DM), a set of metabolic disorders, is characterized by persistent high blood glucose level because of errors in insulin secretion, its action, or both." (PMID 29970150, 2018). "The Planimator app was successfully used in the measurements of surface area of wounds in rats when the induced diabetes was treated with insulin or metformin." (PMID 29505569, 2018). "In the adipose tissue, deletion of Pten resulted in increased insulin sensitivity and resistance to streptozotocin-induced diabetes." (PMID 30038596, 2018). "KT-ratio, log-transformed CRP, group, observed bacterial species, physical activity, diabetes treatment (insulin, oral), mode of HIV transmission (MSM, others), and Framingham 10 year CVD score were included in the multivariate model." (PMID 29712976, 2018). "Experimental studies have provided evidence for the direct beneficial effects of vitamin D supplementation on glucose and insulin homeostasis as well as other metabolic abnormalities in patients with diabetes." (PMID 30627160, 2018). "Diabetes mellitus (DM) is a group of metabolic disorder characterized by hyperglycemia resulting from defects in insulin secretion, insulin action, or both." (PMID 30515216, 2018). "Drosophila has emerged as a useful system for the study of insulin signaling/diabetes and nociception." (PMID 29752280, 2018). "Longer diabetes duration (β = 0.16, p = 0.000), use of multiple daily injections vs. insulin pump (β = -0.10, p = 0.006), and living alone with one parent vs. living with both parents (β = 0.10, p = 0.030) were associated with poorer metabolic control." (PMID 30235290, 2018). "At presentation, both insulin secretion and insulin action are impaired in ketosis prone diabetes patients." (PMID 30918564, 2018). "Diabetes is a chronic and metabolic disease characterized by hyperglycemia resulting from defective insulin secretion and/or insulin resistance." (PMID 29850612, 2018). "However, the association between mannose and insulin sensitivity in those with diabetes remains unknown, although insulin resistance plays an important role in the pathogenesis of type 2 diabetes and dysregulation of plasma mannose levels has been reported in type 2 diabetes." (PMID 30534205, 2018). "Indigenous participants were younger at entry (median age 63.3 [54.7–67.8] vs 69.6 [63.3–75.4], p = 0.005), were more likely to be current smokers (56.3% vs 31.4%, p = 0.041) and have insulin-treated diabetes (18.8% vs 5.2%, p = 0.022)." (PMID 29769031, 2018). "Using type 1 diabetes self-report and current insulin use to classify diabetes type, the percentage of all diabetes cases that were type 1 diabetes fell reasonably within the range of results from other studies (approximately 5%–10%)." (PMID 29596402, 2018). "The use of smart glucometers that do not require a syncing device and even integrating Bluetooth-enabled insulin pens to automatically notate dosage administration can potentially increase adoption of mobile health devices in diabetes care." (PMID 30291085, 2018).
diabetes (continued). "Understanding the disordered systemic IR and defective brain insulin signaling in comorbidity of diabetes and depression has become a topic of concern and public health challenge." (PMID 30622594, 2018). "Metformin is a widely prescribed medication for type 2 and some cases of type 1 diabetes mellitus that opposes hyperglycemia and improves insulin sensitivity." (PMID 30054579, 2018). "Studies have shown that fasting insulin concentrations can be used as a marker as it is known that subjects with higher fasting insulin concentrations have higher risks of developing diabetes." (PMID 30011905, 2018). "Many pregnant women had developed diabetes only since becoming pregnant, and so were novices in self-administering insulin." (PMID 29754584, 2018). "In the present study, we recruited patients with well controlled diabetes to ameliorate the effect of glucotoxicity on insulin sensitivity." (PMID 29970184, 2018). "Together, these multiple hits adversely affect the function of the pancreas and impair insulin release, leading to the development of diabetes." (PMID 30361421, 2018). "Diabetes-specific medical devices (e.g., dip-sticks, insulin pens, insulin pump necessary materials) represented an expenditure of about €793 million, i.e., 35% of all diabetes-specific expenditure." (PMID 28190188, 2018). "Type 2 diabetes mellitus is characterized by insulin resistance and impairment in insulin secretion." (PMID 29898693, 2018). "Liraglutide, a long-acting GLP-1 receptor agonist, is widely used for treating diabetes by stimulating glucose-dependent insulin secretion and suppressing glucagon secretion with a very low risk for hypoglycemia." (PMID 29618348, 2018). "Diabetes mellitus (DM) is a systemic metabolic disease that is characterized by chronic hyperglycemia, hyperlipidemia and other alterations, including insulin resistance or insufficient production." (PMID 30065632, 2018). "Insulin treatment has been shown to reduce the production of NO and iNOS expression in peripherally circulating macrophages in a rodent model of diabetes." (PMID 30148836, 2018). "No studies have evaluated the relationship between adherence to insulin, diabetes-related distress, and trust in physician among persons with diabetes." (PMID 29520741, 2018). "Diabetes adapted tools identify eating disorder behaviours that are unique to T1DM, such as the underuse or omission of insulin for the purpose of weight loss." (PMID 29744106, 2018). "Diabetes traits explored in expression studies included insulin resistance, insulin sensitivity, T1D, T2D, diabetic nephropathy, diabetic neuropathy and diabetic heart failure (HF)." (PMID 29503662, 2018). "The restoration of deficient β-cell mass by transplantation from exogenous sources or by endogenous regeneration of insulin-producing cells would undoubtedly be a worthwhile therapeutic goal that will significantly ameliorate diabetes and its complications." (PMID 30532775, 2018). "Average gestation was 26.6 ± 6.8 weeks (mean ± standard deviation), age was 30.5 ± 5.1 years, diabetes duration was 13.1 ± 7.3 years for T1D and 3.2 ± 2.5 years for T2D, and 49/74 (66.2%) used insulin to manage their diabetes." (PMID 29470094, 2018). "Study participants were insulin-treated adult patients with type 1 diabetes mellitus (T1DM) or type 2 diabetes mellitus (T2DM) from CEE." (PMID 29524189, 2018). "It is generally considered as non-insulin dependent form of diabetes and comprises of 1–5% of total diabetes." (PMID 29867778, 2018). "The free glibenclamide concentration in βV59M mice must be at least 100nmol/l if it is to stimulate insulin release and control the animal’s diabetes." (PMID 29772022, 2018). "DM is characterized by insulin resistance and impaired insulin secretion, and the resulting long-term hyperglycemia in diabetics leads to many ophthalmic complications, including retinopathy, cataracts, uveitis, and keratopathy." (PMID 30453691, 2018).
diabetes (continued). "In general, patients diagnosed with diabetes showed sustained insulin secretion in response to the oral glucose load, although their insulin sensitivity and glycemic responses varied." (PMID 30040822, 2018). "In a recent study that focused on the level and determinants of diabetes knowledge in Zimbabwean adults with diabetes mellitus, we reported that patients with diabetes had major knowledge gaps regarding diet, glycemic control and insulin use." (PMID 30050608, 2018). "Today treatment of diabetes with phytomedicine is mostly used in underdeveloped countries, where access to synthetic drugs and insulin is limited, or in industrialized countries with tradition in the use of alternative medicine, such as China and India." (PMID 30158993, 2018). "Mean diabetes duration was 10.21 (SD 4.39; range, 2-17) years; mean age at diagnosis was 9 (SD 4.42; range, 3-17) years, and 80% (16/20) participants were insulin pump users." (PMID 30401674, 2018). "Insulin signaling in sensory neurons has also been suggested to participate in pathophysiological alterations induced by diabetes." (PMID 30364236, 2018). "People with diabetes on intensive insulin therapy need sufficient glycaemic control to prevent the onset or progression of diabetic complications." (PMID 29402319, 2018). "The objective of this study was to know the level of insulin adherence and to identify factors affecting insulin adherence among diabetes mellitus patients in Felege Hiwot Referral Hospital, Bahir Dar, Northwest Ethiopia." (PMID 29751841, 2018). "insulin knockout zebrafish recapitulate core characteristics of diabetes and survive only up to larval stages." (PMID 30520733, 2018). "It is involved in the synthesis, storage, and release of insulin, which suggests the critical role of this microelement in the progression of type-2 diabetes mellitus, atherosclerosis, and metabolic syndrome (MS)." (PMID 28965330, 2018). "Mulberry leaf as a traditional Chinese medicine treating diabetes mainly by enhancing the insulin sensitivity of peripheral tissues." (PMID 30131712, 2018). "Diabetes mellitus (DM) occurs due to an abnormality in blood glucose metabolism in which production or activity of insulin is adversely affected." (PMID 29937497, 2018). "Inhibition of Hsp90 has been shown to improve glucose tolerance and insulin sensitivity in mouse models of diabetes." (PMID 29434648, 2018). "Regarding specificities of diabetes and its treatment, the psychological resistance to insulin regimens is an important issue." (PMID 29636825, 2018). "Children with diabetes can avoid substantial weight gain by optimising insulin management, adhering to individually tailored nutrition advice and regular participation in physical activities." (PMID 29549246, 2018). "The available treatment modality for diabetes is essentially the treatment of hyperglycemia and this relied on insulin and other pharmacological agents such as sulfonylureas and metformin." (PMID 30563087, 2018). "Because there were few populations with diabetes in this study, further analysis of the influence of fatty pancreas on insulin secretion in diabetic patients is necessary." (PMID 30571730, 2018). "In most patients with permanent neonatal diabetes, lifelong insulin therapy is required, and management follows guidelines for T1DM." (PMID 29508275, 2018). "Diabetes is classified as chronic diseases that occur when the insulin production in the pancreas is disrupted or the cells cannot the ability to use the insulin." (PMID 30697319, 2018). "For patients with metabolic syndrome and type 2 diabetes mellitus, agonists of imidazoline receptors are suitable too, especially for their stimulation of insulin secretion, decrease of sympathetic hyperactivity, and inhibition of kidney sodium reabsorption." (PMID 29805801, 2018).
diabetes (continued). "Factors associated with a significantly increased rate of CAUTI were age, cancer, diabetes treated with insulin, poor or very poor ADL score, length of stay, and hospital case volume." (PMID 29093305, 2018). "The groups were largely similar in the rate of preoperative comorbidities including COPD (9% vs. 3%, p = 0.18) and diabetes (21% vs. 20%, p = 0.92), however there was a higher rate of insulin use in the pre-pathway group (p = 0.04)." (PMID 30592736, 2018). "These participants had similar age, diabetes duration and HbA1c to participants with retained C-peptide but had lower BMI and time to insulin and greater use of prandial insulin." (PMID 28983693, 2018). "Elevated blood free fatty acids (FFAs), as seen in obesity, impair muscle insulin action leading to insulin resistance and Type 2 diabetes mellitus." (PMID 30400151, 2018). "The media reports highlighted the significant costs of medications for example, as much as half of a household’s monthly income for one vial of insulin to treat diabetes." (PMID 29463270, 2018). "In conclusion, in a large series of Italian outpatients with diabetes treated with an insulin basal-bolus regimen, the b/T ratio was lower than 50% and significantly higher in DM1 than in DM2 patients." (PMID 30918874, 2018). "Bhattacharya R, Zhou S, Wei W, Ajmera M, Sambamoorthi U. A real-world study of the effect of timing of insulin initiation on outcomes in older medicare beneficiaries with type 2 diabetes mellitus." (PMID 29527102, 2018). "All of the diabetic subjects in this study were newly diagnosed; therefore, only 1% of subjects in the diabetes group were exposed to insulin and very few cases of PaC (8 cases) developed." (PMID 29946194, 2018). "In the total study population, there was a positive relationship between insulin secretion (assessed as DIo) and family history of diabetes, with higher beta coefficients for FH++ compared with FH+ individuals." (PMID 29274011, 2018). "In light of the persistent barriers contributing to delays in diabetes management with insulin, there is an urgent need for a simplified and practical approach to the initiation and intensification of insulin." (PMID 29476414, 2018). "Decision trees and logistic regressions both select use of insulin and duration of diabetes as the most discriminative features to predict diabetic retinopathy." (PMID 30367589, 2018). "In literature, the role of these markers in the development of diabetes and insulin has been well documented." (PMID 30524684, 2018). "Duration within different glucose ranges and number of hypoglycemic and hyperglycemic events are broken down by diabetes type and insulin use." (PMID 29470094, 2018). "Regarding their treatment of diabetes, eight donors were treated with diet therapy, five donors were treated with oral therapy, and one donor was treated with insulin." (PMID 29027035, 2018). "The kidney is also an insulin-sensitive organ involved in normal glucose homeostasis and enhanced gluconeogenesis during diabetes." (PMID 30003110, 2018). "Our study has shed new light on PI4KIIα function and mechanism in diabetes and identified PI4KIIα as an important regulator of insulin secretion." (PMID 29577067, 2018). "The percentages of patients with CSDME were higher in patients who had diabetes for more than 10 years, were taking insulin only, and had an A1c of greater than 10%." (PMID 29924846, 2018). "There were two donors with diabetes with hemoglobin A1c levels higher than 6.5%, urine albumin excretion rate of more than 30 mg/day, or a history of treatment with insulin." (PMID 29027035, 2018). "In the present study, we aimed to evaluate the suitability of the diabetes-related miR-375 and miR-9, which are important regulator of insulin secretion, as earlier blood biomarkers for detecting prediabetes and T2D." (PMID 29373500, 2018).
diabetes (continued). "Permanent neonatal diabetes (PND) caused by mutations in KCNJ11 or ABCC8 can be managed with high-dose sulphonylurea therapy in > 90% of cases, negating the need for insulin therapy and associated complications in affected neonates." (PMID 30377832, 2018). "Hyperglycemia occurs because of impaired insulin action in diabetes as a result of insulin resistance and impaired insulin secretion." (PMID 29942356, 2018). "The effects of kiwifruit on metabolic markers of cardiovascular disease and diabetes are also investigated, including studies on glucose and insulin balance, bodyweight maintenance and energy homeostasis." (PMID 29470689, 2018). "The thematic synthesis identified that the support of diabetes specialist teams, can help primary care HCPs to deliver insulin support." (PMID 29788908, 2018). "Sodium tungstate (NaW) is an inorganic salt that exerts potent insulin-mimetic and antidiabetic actions in animal models of diabetes by normalizing hepatic glycogen metabolism and blood glucose levels." (PMID 30003110, 2018). "In 15 subjects, the anti-diabetes medication was gradually reduced during dietary intervention, and 2 subjects, 1 on both oral hypoglycemic agents and insulin, had their medication cancelled." (PMID 29599686, 2018). "No significant between-group differences were observed with regard to duration of diabetes, glycemic control, insulin dosage, or presence of hypertension, nephropathy, or retinopathy." (PMID 29694634, 2018). "Regarding the diabetic phenotype, both patients had insulin-dependent diabetes mellitus with a similar severity of insufficient insulin secretion in their thirties." (PMID 29343702, 2018). "The topics ‘dietary habits’ and ‘physical activity’ can also be used to stimulate diabetes self-management in the non-insulin users." (PMID 30348142, 2018). "When the formation of mTOR signaling and complex formation is disturbed, the effects contribute to common pathobiologies found in cancer and diabetes including cell stress, apoptosis, metabolic shifts, protein sysnthesis dysregulation, and insulin signaling." (PMID 29529022, 2018). "The accurate estimation of the meal content by the system based on the voice description provided by the person with diabetes is one of the necessary conditions to effectively help such a person calculate the proper insulin dose to compensate for the meal." (PMID 29690520, 2018). "Basal-bolus regimen is the most recommended approach for insulin-treated patients with diabetes, as it reflects the physiological insulin secretion and improves glycemic control more safely than other insulin regimens." (PMID 30918874, 2018). "Clinical studies demonstrated that TZDs improve whole-body insulin sensitivity in type 2 diabetes patients, and therefore they were approved for the treatment of diabetes." (PMID 29793507, 2018). "The reported mechanism(s) of decreased muscle strength in diabetes include insulin resistance, insulin signaling, neuropathy, and hyperglycemia." (PMID 30077183, 2018). "Overall, these data highlight that the described gliclazide MR regimen is an effective option for a wide variety of non-insulin treated individuals with diabetes and inadequate glycemic control." (PMID 29651307, 2018). "The glucose concentrations after insulin administration (average of measurements at 30, 60, and 120 minutes) did not change as compared to baseline in lean men or in those with diabetes." (PMID 30515210, 2018). "The majority of CHI patients with diabetes were treated with insulin (85.2% [70.9–99.5] at diabetes onset, and 90.5% [81.2–99.7] at follow-up)." (PMID 30577875, 2018). "Except for BMI, TG and SG were well-matched for duration of diabetes, HbA1c, baseline insulin dose, lipid profile and creatinine." (PMID 30347712, 2018). "Diabetes is characterized by insulin deficit or insulin insensitivity and consequently produces high blood sugar levels which are associated with other disorders." (PMID 30558268, 2018).